GRAP2 (GRB2 related adaptor protein 2)
Description:
Interacts with SLP-76 to regulate NF-AT activation. Binds to tyrosine-phosphorylated shc.
Synonyms: GRB2L; GADS; GRID; Grf40; GrbX; GRBLG; Mona; GRAP-2; GRPL; P38
Tractability: Antibody: its Gene Ontology location is reachable by antibodies, with high confidence. PROTAC: ubiquitination databases record sites on it; its protein half-life has been measured.
Gene: Protein-coding gene on chromosome 22 (39,901,084 to 39,973,721, forward strand). Ensembl gene ENSG00000100351.
Subcellular location: Nucleus; Cytoplasm; Endosome
Subcellular location (Human Protein Atlas): Cytosol; Nucleoplasm; Plasma membrane
Pathways (Reactome):
Immune System: Co-stimulation by CD28; DAP12 signaling; FCERI mediated Ca+2 mobilization; FCERI mediated MAPK activation; FLT3 Signaling; Generation of second messenger molecules; Signaling by CSF1 (M-CSF) in myeloid cells
Signal Transduction: Signaling by SCF-KIT
Gene Ontology:
Molecular function: protein binding; phosphotyrosine residue binding
Biological process: cell-cell signaling; Ras protein signal transduction; regulation of MAPK cascade; signal transduction
Cellular component: cytoplasm; cytosol; endosome; nucleoplasm; nucleus; plasma membrane
Genetic constraint (gnomAD): Loss-of-function variants: 25 observed, 31.24 expected, observed/expected ratio (o/e) 0.8, 90% interval 0.58 to 1.12. The upper end of that interval is the gene's LOEUF score, 1.12, which puts it in group 4 of 6, group 1 being the genes least tolerant of losing a copy. Missense variants: 262 observed, 321.72 expected, observed/expected ratio (o/e) 0.81, 90% interval 0.74 to 0.9. Synonymous variants: 127 observed, 131.53 expected, observed/expected ratio (o/e) 0.97, 90% interval 0.83 to 1.12.
Homologues: Orthologues: chimpanzee GRAP2 (99% identical), macaque GRAP2 (99% identical), dog GRAP2 (89% identical), pig GRAP2 (88% identical), guinea pig GRAP2 (88% identical), mouse Grap2 (86% identical), rat Grap2 (85% identical), rabbit GRAP2 (60% identical), zebrafish grap2a (45% identical), tropical clawed frog grap2 (44% identical), zebrafish grap2b (37% identical), Caenorhabditis elegans nck-1 (16% identical), and 1 more. Paralogues in human: GRB2 (34% identical), GRAP (32% identical), NCK2 (18% identical), NCK1 (18% identical), SLA2 (17% identical), DAPP1 (17% identical), SH2D5 (17% identical), SLA (16% identical), GRAPL (15% identical).
Diseases named in the same sentence as GRAP2 in open-access papers:
GRAP2 is named in the same sentence as 26 diseases in open-access papers, as found by Europe PMC text mining. Sharing a sentence is not in itself a finding about the gene and the disease. The quoted sentences say what the papers report.
breast carcinoma (2 papers, 2024). "The suitabilityof changes in GRAP2 gene methylation levelsas blood diagnostic markers for breast cancer requiresfurther discussion." (PMID 39139156, 2024). "Our findings propose that the genes RANBP3, LCP2, and GRAP2, located at the identified methylation sites, hold significant potential as molecular markers in blood for the supplementary diagnosis of breast cancer." (PMID 39139156, 2024). "Subsequently, we investigated the methylation status of the genes Ran-binding protein 3 (RANBP3), Lymphocyte cytoplasmic protein 2 (LCP2), and GRB2 related adaptor protein 2 (GRAP2), situated at the specified sites, using cancer and canceradjacent tissues from 17 breast cancer patients." (PMID 39139156, 2024). "Our research, however, indicates thatwhile GRAP2 is highly expressed in nontriple-negativebreast cancer, it exhibits no relation to methylation intriple-negative breast cancer." (PMID 39139156, 2024).
schizophrenia (2 papers, 2023). A major psychotic disorder characterized by abnormalities in the perception or expression of reality. "There have been a few studies which suggested the association between GRB2/GRAP2 and schizophrenia, but we suspect GRAP2 might be actively involved in integrating and transmitting the effects of gene deletion leading to the expression of neuropsychiatric diseases." (PMID 37872602, 2023).
/T cell lymphoma (1 paper, 2023). "GRAP2 has been implicated in extranodal NK/T cell lymphoma, a rare and aggressive subtype of T cell or NK lineage extranodal lymphoma." (PMID 37379307, 2023).
Autoimmunity (1 paper, 2008). The occurrence of an immune reaction against the organism's own cells or tissues. "Neither Mef2c, Grap2, or Plekha was previously linked to tolerance or autoimmunity." (PMID 19578517, 2008).
B cell lymphoma (1 paper, 2023). "GARP2 is a specific marker of T lineage differentiation; it was interesting to observe a variant in this gene in a case affected with CLL, suggesting a role of GRAP2 in B cell lymphoma as well." (PMID 37379307, 2023).
dengue (1 paper, 2022). "Of interest, we observed that several predictive genes of severe dengue, including GYG1, TOR3A, SPON2, GRAP2 and GBP2, were also highly transcribed in the ASCs and effector T cells at Day −1 in our dataset." (PMID 35345453, 2022).
lung adenocarcinoma (1 paper, 2023). A carcinoma that arises from the lung and is characterized by the presence of malignant glandular epithelial cells. "Similarly, GRAP2 was implicated in T cell-mediated immune responses, as well as in medullary thyroid cancer and lung adenocarcinoma prognosis." (PMID 37143087, 2023).
myeloma (1 paper, 2024). "Hence, it can be postulated that RGS1 is a myeloma driver gene that exerts its oncogenic activity via suppressing p38α mediated antagonism of the GRAP2/JNK-cJun pathway." (PMID 38514625, 2024).
Noonan syndrome (1 paper, 2017). Noonan Syndrome (NS) is characterized by short stature, typical facial dysmorphism and congenital heart defects. "Four of the proteins are linked to various forms of the Noonan syndrome (CBL, MAP2K1, RAF1 and SOS), 5 to various types of tumors (MAPK1, PRKCQ, ABL1, GRAP2 and RAS) and one to an autoimmune disorder (RASGRP1)." (PMID 28448599, 2017).
pancreatic cancer (1 paper, 2020). "The methylation status of GRAP2, ICAM3, A2ML1, MUC1, and MUC4 can influence the expression of these genes, which is associated with survival of pancreatic cancer." (PMID 33302876, 2020).
cancer (10 papers, 2010 to 2024). A tumor composed of atypical neoplastic, often pleomorphic cells that invade other tissues. "Additionally, it is the initialinvestigation to validate the association betweenRANBP2, LCP2, and GRAP2 gene methylation andbreast cancer." (PMID 39139156, 2024). "Our analysis revealed that RANBP3, LCP2, and GRAP2 genes exhibited significant methylation differences between cancer and cancer-adjacent tissues." (PMID 39139156, 2024). "GRAP2 is also found to be a candidate tumor suppressor, and it is recognized to be a prognosis prediction marker for different types of cancers, which can regulate tumor cell sensitivity to immunotherapy." (PMID 32968155, 2020). "A ROC curve showed that when the sensitivitywas 86.67% (RANBP3), 82.35% (LCP2) and88.24% (GRAP2), the specificity of breast cancerdiagnosis was 93.3%; the sensitivity of identifyingbreast cancer patients by the comprehensive methylationlevel of the three genes was 94.1%, with aspecificity of 93.3%." (PMID 39139156, 2024). "Similarly, significantdifferences were found in GRAP2 gene methylationlevels between cancer-adjacent tissues and cancertissues among different molecular subtypes(P=0.000, P=0.000, P=0.000, Tukey HSD)." (PMID 39139156, 2024). "Within the list of top differentially expressed genes, in the UCHL1 KDs we found downregulation of the Wnt targets POSTN, SP7, and DLL1, of the transporter ABCA4, of the homeobox gene DLX4, and of genes recently linked to cancer progression ACTA2, AQ4, GRAP2, and ALK." (PMID 28472177, 2017). "Therefore, we believe that GAPT and GRAP2 are involved in the activationof MAPK and growth factor-induced cell proliferation and differentiation, which areoften associated with the development of cancer." (PMID 29489999, 2018).
tumor (9 papers, 2014 to 2024). "GRAP2 is a tumour suppressor gene involved in T cell signalling, development and regulate NF-AT activation." (PMID 37379307, 2023). "Grap2 and cyclin D1 interacting protein (GCIP) has been recognized as a putative tumor suppressor, but the molecular mechanisms underlying its anti-tumor properties remain undefined." (PMID 24970809, 2014). "Indeed, it was observed that it is able of binding the protein GCIP (interacting protein cyclin D1 and GRAP2), which is a tumor suppressor localized in the nucleus, which inhibits the phosphorylation of RB (retinoblastoma protein)." (PMID 25889931, 2015).
hematopoietic cancers (1 paper, 2024). "In 3 independent studies, ZAP70, FYN, GRAP2, ITK, and CD247 (encoding CD3ζ) were highly upregulated in patients with T-ALL compared with individuals acting as healthy controls or people with other hematopoietic cancers, similar to our murine study." (PMID 38618957, 2024). "Furthermore, we found that expression levels of ZAP70, FYN, GRAP2, ITK, and LCK as well as two further TCR pathway kinases, PLCG1 and LAT, were highest in human T-ALL cell lines compared with other hematopoietic cancer lines." (PMID 38618957, 2024).
GRAP2 also shares sentences with these, for which no sentence is quoted: blood cancer (1 paper); COVID-19 (1); hepatocellular carcinoma (1); infection (1); liver cancer (1); lung carcinoma (1); medullary thyroid cancer (1); neurodegenerative disease (1); Parkinson disease (1); rheumatoid arthritis (1); thymoma (1); type B thymomas (1); viral infection (1).